IFNG (interferon gamma)
Diseases named in the same sentence as IFNG in open-access papers (continued):
Sharing a sentence is not in itself a finding about the gene and the disease.
cancer (continued). "Consistently, GSEA-Hallmark analysis reveals significantly elevated enrichment scores for immune-associated and cancer-related signaling pathways, including epithelial-mesenchymal transition, Interferon-gamma response, inflammatory response, and IL6/JAK/STAT3 pathways." (PMID 38763954, 2024). "Consequently, upon IFNγ exposure, such mutations would lead to increase expression of PD-L1, leading to cancer cell immunoediting and immune escape." (PMID 38903504, 2024). "Several studies have confirmed the protective role of γδ T cells in transplantable or spontaneous cancer models, and their antitumor function is closely associated with their production of interferon γ (IFNγ) and tumor necrosis factor (TNF), and/or their cytotoxic potential." (PMID 39309735, 2024). "Nevertheless, ILC1s are potent producers of the type 1 cytokine IFNγ, which has well-established anti-tumoural functions, and patients with cancer that express a high IFNγ-related signature are associated with improved prognosis and response to immunotherapies including immune checkpoint inhibitors." (PMID 38745765, 2024). "The GLMS was positively correlated with cancer hallmark pathways including bile acid metabolism, xenobiotic metabolism, and peroxisome and negatively correlated with pathways such as interferon gamma response, allograft rejection, apoptosis, and inflammatory response (P < 0.05)." (PMID 35600382, 2022). "This appeared partly due to enrichment of JAK1 truncating frameshift mutations, which were associated with reduced IFNγ response in human cancers, loss of IFN signalling in cell lines, and which have recently been shown to predict lack of response to immunotherapy in EC." (PMID 35262923, 2022). "Moreover, six cancer hallmark pathways contained interferon gamma response, protein secretion, interferon alpha response, MTORC1 signaling, JAK STAT3 signaling, and inflammatory response actively associated with the low-risk group." (PMID 35422861, 2022). "Although the association of IFNγ signaling as a single variable with cancer recurrence was more significant than that of TNFα signaling, the combined effects of TNFα/TGFβ signaling were more significant than combination of IFNγ/TGFβ signaling in BLBC." (PMID 33767579, 2021). "PD-1 blockade is associated with an increase in pro-inflammatory cytokine activity, such as increased circulating levels of interferon-gamma (IFNγ) and interleukin-10 (IL-10), which have positive implications for cancer treatment but can increase the risk of secondary irAEs." (PMID 34201529, 2021). "Since the interferon gamma response pathway was the most over‐represented cancer hallmark in the COSMOS network solution, we investigated further the relevance of the mechanistic hypothesis connecting members of this pathway." (PMID 33502086, 2021). "Furthermore, from the 245 HLA-I cancer-associated antigens common to both conditions, many were represented by more peptides following IFNγ treatment (A similar trend was observed across the total common source antigen pool)." (PMID 33968037, 2021). "Second, it has been shown that immunotherapy may lead to the selection of escape variants; i.e., the outgrowth of cancer cells with defects in downstream IFNγ signaling, or with genetic hits in HLA expression." (PMID 32471301, 2020). "The ability to eliminate cancer cells was also associated with increased IFNγ-producing CTLs11,29." (PMID 31776459, 2019). "Furthermore, we have shown that altering responsiveness of the cancer cells to IFNγ causes complex multifaceted changes in the microenvironment." (PMID 31133614, 2019).
cancer (continued). "Besides its established role in contributing to anti-tumor immunity, IFNγ is also implicated in mediating resistance to various cancer therapies, including anti-PD1 therapies via downregulation of MHC I molecules." (PMID 31355143, 2019). "In recent years, IFNγ/STAT1 pathway has been linked to metastatic progression of cancers." (PMID 31113461, 2019). "Interestingly, inflammatory cytokines, especially IFNγ, also cause dynamic adaptive changes of cancer cells." (PMID 26981247, 2016). "In humans, there is an increasing evidence that cytokines, including tumor necrosis factor alpha (TNF-α), interleukin (IL)-1, IL-6, IL-8 and interferon gamma (IFN-γ) may participate in the cause or the development of cancer cachexia." (PMID 20037740, 2009). "Various cytokines, such as tumour necrosis factor-α or interferon gamma, have been shown to increase transcripts of ubiquitin in skeletal muscle, but the importance of these cytokines as mediators of the weight loss in human cancer cachexia is controversial." (PMID 15213711, 2004). "Interestingly, some studies show that the primary response to anti-CTLA4 antibodies required a high-level exposure of MHC-1 on the surface of cancer cells at baseline; on the other hand, the response to anti-PD-1 antibodies is linked to a pre-existing IFNγ transcriptome signature." (PMID 34638337, 2021). "Recently, Cekay et al24 showed that a novel synergistic interaction of IFNγ with second mitochondria‐derived activator of caspases (Smac) mimetics that antagonize x‐linked Inhibitor of Apoptosis (XIAP) to induce necroptosis in apoptosis‐resistant cancer cells where caspase activation is suppressed." (PMID 30039553, 2018). "While the specific IFNγ production to tumor associated antigen (TAA) would highlight the exclusive response to cancer antigen, IFNγ response to common viral antigens in Sweden such as CMV-pp65 and EBNA-1 (prevalence above 80%) may reflect general immunological balance versus immune exhaustion." (PMID 29970101, 2018). "Therefore, we hypothesized that inhibition of cell cycle progression-related genes by IFNγ could provide clinical benefits through the reversal of the cancer hallmark." (PMID 28526810, 2017). "Although the combination of hypoxia and cancer cell/CAF-derived factors enhances IFNγ and granzyme B expression in CD8+ T cells on a per-cell basis, the overall number of functional effector T cells is markedly reduced." (PMID 42192869, 2026). "Members of the IL-1 family participate in cancer progression and stimulate other pro-inflammatory cytokines, such as IL-18, which stimulates interferon gamma (IFN-γ) in several cells, including NK cells and type 1 innate lymphoid cells (ILC1)." (PMID 41596472, 2026). "The finding from this study demonstrates an important role of IFNγ in inducing the anti-cancer activity of Tconv cells, an underappreciated role of IFNγ in ACTs." (PMID 39876025, 2025). "The unique activation of IFNγ-JAK-STAT signaling in cancer cells following arginine deprivation prompted us to examine the potential therapeutic effect of the JAK1/2 inhibitor ruxolitinib." (PMID 41511309, 2025). "NK cell–produced TNFα and IFNγ induce ICAM-1 upregulation on K562 cancer cells, which then enhances the cytotoxicity of cancer cells by promoting their conjugate formation with NK cells." (PMID 41128663, 2025). "IRF1, a classical downstream target of IFNγ, functions as a transcription factor critical in mediating IFNγ-induced anti-proliferation, apoptosis, invasion inhibition, and antitumor immunity in cancer." (PMID 41218553, 2025). "And the finding demonstrated a strong correlation between elevated levels of immune checkpoints and the SREBF1 in ACC, notably KIR2DL3, IL2RA, CD80, IFNG, BTN3A2, and IL1A, also IFNA1 wass significantly associated with SREBF1 in the majority of cancers." (PMID 40668814, 2025). "IFNγ and TNFα have been previously explored in clinical trials for cancer therapy due to their potent immune-stimulatory effects." (PMID 40547518, 2025).
cancer (continued). "Apart from IFNγ, PD-L1 expression in various cancer cells can be induced by different immunostimulatory cytokines such as IL-6, INF-α and -β and TNF or immunosuppressive cytokines such as IL-10 and TGFβ." (PMID 39941003, 2025). "This difference in sensitivity to IFNγ between cancer cells is dependent on the baseline PD-L1 expression level." (PMID 40001596, 2025). "The expression of PD-L1 in each cancer cell type was upregulated even at low concentrations of IFNγ (6.25 ng/mL), suggesting that cancer cells are sensitive to IFNγ stimulation." (PMID 40001596, 2025). "Interferon-gamma (IFN-γ), the sole member of the type II interferon family, is a crucial cytokine in immune system regulation, particularly in cancer immunosurveillance." (PMID 40002189, 2025). "Based on evaluation standards from multiple layers, W-GTF01 (No.8 compound) was confirmed as a potent inhibitor of MGAT1 activity and stimulator of CD8+ IFNγ-producing T-cell response, leading to lowest cancer cell survival." (PMID 40229283, 2025). "XmAb808 avidly bound cancer cells and stimulated IL2 and IFNγ secretion from T cells cocultured with cancer cells engineered to deliver Signal 1 to T cells via a surface-expressed anti-CD3 antibody." (PMID 39301613, 2025). "When cancer cells were cultured alone, birinapant synergized with supplemented IFNγ to induce STING mRNA and protein expression in LKB1-mut cancer cells." (PMID 40057483, 2025). "The suppressive effect of HIF1α on IFN-1 (IFNα and IFNβ) or IFN-2 (IFNγ) was described by others in a hypoxic microenvironment in cancer as well as in SARS-CoV-2 infection." (PMID 40570045, 2025). "The inhibitory effect of siPDL1 and lipid-siPDL1s on PD-L1 protein expression in cancer cells upon IFNγ stimulation was examined by performing confocal fluorescence microscopy and western blot analysis." (PMID 40001596, 2025). "Our results have shown that TAK‐228 also holds therapeutic potential by enhancing IFNγ's cytotoxic effects on cancer cells, thereby reinforcing the immune response against cancer." (PMID 39258533, 2025). "Cancer serum was incubated with control IgG or neutralizing antibodies targeting IL-6, G-CSF, TNFα, and IFNγ before injection into MDX mice." (PMID 41322654, 2025). "Nevertheless, to date there is no study focusing on the interplay of the inflammatory response and the interferon-gamma pathways in cancer progression, warranting further investigation." (PMID 40458391, 2025). "Type II interferon (IFNγ) signaling is essential for innate immunity and critical for effective immunological checkpoint blockade in cancer immunotherapy." (PMID 40586312, 2025). "For example, research has shown that IFNγ can enhance the sensitivity of cancer cells to ferroptosis inducers by upregulating the expression of iron transporters and promoting the accumulation of intracellular iron, thereby sensitizing cells to ferroptosis." (PMID 39820341, 2025). "NK cells from STS patients were less functional, showing reduced degranulation and lower production of IFNγ, both essential for killing cancer cells." (PMID 40805205, 2025). "Affected by cancer-derived exosomes, these NK cells showed low production of interferon gamma (IFN-γ) and poor NKG2D-dependent killing function." (PMID 41294803, 2025). "Further analyses of the splenocytes from the treated mice revealed a marked increase in the percentages of IFNγ+ T cells compared to those from untreated control mice, indicating a robust anti‐cancer immune response induced by the local TACTIC treatment." (PMID 39999304, 2025). "Interferon-gamma (IFN-γ) is a critical cytokine in the activation of cellular immunity, enhancing the immune system’s ability to recognize and eliminate cancer cells." (PMID 39941844, 2025). "The important role of IFNγ in the context of cancer is evident but also complex and not fully understood." (PMID 41078003, 2025).
cancer (continued). "Another interesting result that they showed in their study was that the enhanced IFNγ observed in the treatment of NK cells + ferumoxytol mediated ferroptosis induced the PD-L1 upregulation in cancer cells." (PMID 41339932, 2025). "Despite variations in IFNγ sensitivity among the three cancer cell lines, PD-L1 expression was upregulated in all examined cells." (PMID 40001596, 2025). "Cytotoxic T-cell-secreted IFNγ also contributes to cancer cell immunoediting by inducing copy number rearrangements that directly lead to loss of antigen and immune escape." (PMID 40663561, 2025). "Researching drugs that upregulate IFNγ-dependent PD-L1 expression, offers a promising strategy in cancer therapy." (PMID 40264756, 2025). "We identified CXCL13 + CD8 + T cells expressing GMZB and IFNG—cytotoxic T lymphocytes (CTLs)—as the cells that attack cancer cells following PD-L1-CRT." (PMID 40670667, 2025). "T-lymphocytes directly attack cancer cells while B lymphocytes act via cytokines like interferon-gamma and tumor necrosis factor-alpha." (PMID 41394347, 2025). "When considering SFV vector therapeutic expectations, SFV/TNFα and SFV/IFNγ serve different functions in cancer treatment." (PMID 40547518, 2025). "Specifically, trastuzumab upregulates PD-L1 levels in HER2-overexpressing cancer cells by activating the extrinsic pathway, where immune effector cells release IFNγ." (PMID 40028325, 2025). "In the regulation of sensitivity of cancer cells to T cell-mediated killing, positive selection was found in DNA Binding transcription factor activity, IFNγ signaling, necroptosis, RIPK1-mediated necrosis, and the TNF pathway." (PMID 39868264, 2025). "IL2 supports T-cell proliferation, survival, and differentiation, whereas IFNγ enhances antitumor immunity by promoting antigen presentation and by directly killing cancer cells." (PMID 39301613, 2025). "Following training, we co-cultured wild-type N2a cancer cells with either untrained or trained splenocytes for 48 hours and quantified IFNγ production via ELISA assays." (PMID 40552293, 2025). "For instance, CD8+ T cells suppress xCT expression in cancer cells via IFNγ, thereby sensitizing them to ferroptosis." (PMID 40619484, 2025). "Even exposure to low concentrations of IFNγ (6.25 ng/mL) also increased PD-L1 expression in cancer cells." (PMID 40001596, 2025). "Accordingly, the RNAi effects of lipid-siPDL1s were examined at the highest PD-L1 expression level in each cancer cell line stimulated with 100 ng/mL IFNγ." (PMID 40001596, 2025). "The ISG.RS has been posited as a resistance signature to anti‐PD‐1 therapy, predominantly expressed in cancer cells, yet influenced by IFNG.GS within CD8 T cells." (PMID 40165405, 2025). "Various cancer cell types exhibit differential expression of cancer immune checkpoints, including PD-L1, and IFNγ stimulation substantially modulates PD-L1 expression." (PMID 40001596, 2025). "This leads to increased numbers of CD4+IFNγ+, CD8+IFNγ+, and CD11b+F4/80+ immune cells in the tumors, ultimately helping to destroy cancer cells." (PMID 40006729, 2025). "Upregulation of PD-L1 enhances the susceptibility of cancer cells to the combination of CD64-CR and atezolizumab through specific production of IFNγ." (PMID 39962623, 2025). "Cancer cells in particular exhibited a substantially weaker interferon gamma response post treatment in growing ribociclib-resistant tumors compared to ribociclib-sensitive shrinking tumors (est = −0.027, df = 1913, t = −20.2, p < 0.0001)." (PMID 40032842, 2025). "A small percentage of 1B5 cells, 1.31%, produced TNFα alone or in combination with IFNγ when co-cultured with unpulsed FM3 cancer cells, which increased to 64.7% when co-cultured with peptide-pulsed cancer cells." (PMID 40333248, 2025). "Inflammatory mechanism exploitation: Cancer cells can hijack inflammatory processes by inducing immune cells to secrete interferon-gamma." (PMID 40924249, 2025).
cancer (continued). "Lipid-siPDL1s markedly suppressed PD-L1 protein expression across all three cancer cell types, even when IFNγ stimulation enhanced PD-L1 expression, with the inhibitory effect lasting for at least 96 h." (PMID 40001596, 2025). "This subset has been shown to display cytotoxic activity and promote immune surveillance against cancer, often through the secretion of interferon-gamma (IFN-γ)." (PMID 40236336, 2025). "Successful anti-PD-1 cancer immunotherapy requires crosstalk between DCs and T cells with IL-12p40 being produced by DCs upon sensing interferon-gamma (IFN-γ) released from neighbouring T cells." (PMID 40868162, 2025). "CD8 + T cell activation was confirmed by Interferon gamma (IFN-γ) production in monoculture p (<0.05) and coculture with cancer cells when treated with IL-15 (p < 0.0001)." (PMID 40032842, 2025). "It is well known that IFNγ binding to its receptors on cancer cells can triggers the IFNγ/JAK/STAT pathway that can result in increased PD‐L1 expression as a defense mechanism against T cell attacks in most tumors." (PMID 39258533, 2025). "In this study, we also investigated IFNγ-stimulated changes in PD-L1 expression in each cancer cell line." (PMID 40001596, 2025). "In contrast, Cycling GZMA CD4 T cells expressed GZMA and demonstrated a marked upregulation of anti-cancer-related genes, including IFNG, PRF1, and TNFSF10." (PMID 40959273, 2025). "An important consequence of controlling JAK/STAT pathways is the attenuation of interferon-γ (IFNγ) and interleukin-2 (IL-2) signaling, which can impair the recognition and elimination of cancer cells by T cells." (PMID 41302504, 2025). "Immunotherapy-activated CD8+ T cell-released IFNγ induces ferroptosis-specific lipid peroxidation in cancer cells to promote cancer immunotherapy." (PMID 40463869, 2025). "Previous studies have reported that IFNγ produced by T cells converts non-cancer stem cell to cancer stem cells." (PMID 39931080, 2025). "To the best of our knowledge, we noticed for the first time that conditioned medium from NK-92 cells, which contains IFNγ, can sensitize cancer cells to apoptosis triggered by FASLG." (PMID 40512405, 2025). "The important role of IFNG in cancer therapy has been thoroughly validated in numerous clinical trials and animal studies." (PMID 39945555, 2025). "Like IFNγ, perforin is considered to act as an anti-cancer mediator that can control the growth and spread of tumors." (PMID 40895524, 2025). "Some immune checkpoint and MHC-related molecules are known to be up-regulated by IFNγ in lung and other cancers through JAK/STAT signaling." (PMID 40449595, 2025). "Systematic exploration of transcriptional responses to paclitaxel and cancer-associated microenvironmental factors revealed common gene programs induced by paclitaxel, IFNB, and IFNG." (PMID 39905117, 2025). "The cytotoxic capability and IFNγ production exhibited by NK cells are essential to effectively combat cancers." (PMID 40332725, 2025). "Gal-3, a prominent TME modulator, efficiently subverts the elimination of cancer, either directly by inducing apoptosis of immune cells or indirectly by binding essential effector molecules, such as interferon-gamma (IFNγ)." (PMID 40438186, 2025). "Abrogation of cancer-cell responsiveness to IFNγ was sufficient to negate the therapeutic activity of DCP-IL-12/FLT3L in mice, despite the observed enhancement of intratumoral CD8+ T cell infiltration and activation." (PMID 37996514, 2024). "In contrast, the angiostatic cytokine profiles of TNFα, MIG, M-CSF, IL-10, and IFNγ in the host serum revealed a dramatic and significant decrease after day 5 post-implantation of cancer cells." (PMID 39451257, 2024). "Addressing this question, the current study provides evidence that peripheral CD27+ IFNγ-producing γδ T cells consist of an immature Ly6C− population that converts into a mature Ly6C+ population with cancer cell killing capacity." (PMID 38816652, 2024).